EGFR (epidermal growth factor receptor)
Diseases named in the same sentence as EGFR in open-access papers (continued):
Sharing a sentence is not in itself a finding about the gene and the disease.
chondrosarcoma (11 papers, 2019 to 2025). A malignant cartilaginous matrix-producing mesenchymal neoplasm arising from the bone and soft tissue. "To determine whether mTOR is activated in HEMC-SS chondrosarcoma cells and whether this is associated with EGFR activation, we analyzed mTOR phosphorylation status in the absence and presence of the EGFR inhibitor, AG1478." (PMID 31139331, 2019). "We also showed that miR-491-5p is an apoptomiR in chondrosarcoma cells, through the direct inhibition of Bcl-xL and the repression of epidermal growth factor receptor (EGFR) expression." (PMID 37719019, 2023). "Amphiregulin (AR), a ligand of the epidermal growth factor receptor, enhances glutamine metabolism and supports cisplatin resistance in human chondrosarcoma by promoting NADPH production and inhibiting reactive oxygen species (ROS) accumulation." (PMID 37928274, 2023). "Our data revealed that inhibition of EGFR by AG1478 produced arrest in the G0/G1 phase, suggesting that AG1478 exerts growth-inhibitory effects in chondrosarcoma cells by causing G0/G1 cell cycle arrest probably through inhibition of ERK1/2 signaling." (PMID 31139331, 2019). "Altogether, these results support the notion that inhibition of EGFR in chondrosarcoma cells HEMC-SS decreased cell proliferation and migration." (PMID 31139331, 2019). "Up to 20% inhibition in cell proliferation was observed when chondrosarcoma cells were treated with 1 μM of AG1478, indicating that constitutive activation of EGFR sustains the proliferation of the grade III chondrosarcoma cells, CH2879." (PMID 31139331, 2019). "To investigate the mechanism by which AG1478 mediates cell growth inhibition in HEMC-SS chondrosarcoma cells, we performed flow cytometry analysis to determine the effect of EGFR inhibition on cell cycle progression." (PMID 31139331, 2019). "Silencing of EGFR by siRNA efficiently reduced its expression and strongly decreased the phosphorylation of both ERK1/2 and AKT, confirming the key role of EGFR in the activation of downstream signaling pathways in HEMC-SS chondrosarcoma cells." (PMID 31139331, 2019). "To further validate the EGFR immunohistochemistry data, we analyzed the expression and phosphorylation of EGFR in two human-derived chondrosarcoma cell lines, HEMC-SS and SW1353, and in human primary chondrocytes by immunoblot." (PMID 31139331, 2019). "Here, we investigated the activation status of EGFR in chondrosarcoma tumors and studied the effect of inhibition of EGFR in chondrosarcoma cell lines using specific TKI inhibitor and neutralizing antibodies." (PMID 31139331, 2019). "Analysis of the phosphorylation status of EGFR indicated that the receptor is strongly activated in chondrosarcoma cell line HEMC-SS but weakly activated in SW1353." (PMID 31139331, 2019). "Up to 30% inhibition in cell proliferation was observed when chondrosarcoma cells were treated with 5 μM of AG1478, indicating that constitutive activation of EGFR sustains chondrosarcoma cell proliferation." (PMID 31139331, 2019). "Taken together, these data support the blocking of EGFR as new potential treatment for high-grade chondrosarcoma tumors." (PMID 31139331, 2019). "The results clearly show that treatment of chondrosarcoma cells with the EGFR inhibitor strongly reduced the migration of HEMC-SS cells compared to control cells (DMSO)." (PMID 31139331, 2019). "Here, we investigated the activation status of EGFR in chondrosarcoma tumor biopsies and cell lines." (PMID 31139331, 2019). "A dose-dependent inhibition in cell growth of chondrosarcoma cells HEMC-SS was observed following treatment with the EGFR inhibitor AG1478." (PMID 31139331, 2019). "Treatment with AG1478 induces significant cleavage of both Caspase 3 and PARP, indicating that AG1478 induces apoptosis in CH2879 chondrosarcoma cells and suggest that activation of EGFR promote the survival of the tumor cells." (PMID 31139331, 2019).
chondrosarcoma (continued). "For this purpose, HEMC-SS chondrosarcoma cells were incubated with a monoclonal anti-EGFR neutralizing antibody that reacts with external domain of EGFR and the phosphorylation status of ERK1/2 and AKT were monitored by western blot." (PMID 31139331, 2019). "The results revealed that EGFR is strongly expressed in chondrosarcoma cell lines compared to primary chondrocytes." (PMID 31139331, 2019). "Altogether, these data suggest that aberrant activation of ERK1/2 and AKT signaling pathways in chondrosarcoma cells is driven by constitutive EGFR activation." (PMID 31139331, 2019). "miRNAs: miR-342-5p post-transcriptionally inhibits BCL2L1 mRNA in SW1353 chondrosarcoma cells, while miR-491-5p inhibits epidermal growth factor receptor (EGFR) expression, whose spontaneous activation in the absence of ligand is associated with tumor progression." (PMID 37240338, 2023). "This inhibition suggests a possible downstream inhibition of the AKT and MAPK signaling pathways, leading to a decrease in chondrosarcoma cell proliferation and migration, as shown in other studies investigating the inhibition or silencing of EGFR in chondrosarcomas." (PMID 34070455, 2021). "EGFR is constitutively activated in high-grade chondrosarcoma tumors." (PMID 34070455, 2021). "However, prolonged stable disease was achieved for chondrosarcoma patients by combining mTOR inhibitors with liposomal doxorubicin or EGFR, IGF1R, VEGF inhibitors." (PMID 33425984, 2020). "To determine whether such strategy could be considered in the case of chondrosarcoma, we examined whether anti-EGFR monoclonal antibodies are effective in preventing the aberrant activation of ERK1/2 and AKT pathways." (PMID 31139331, 2019). "Unexpectedly, phospho-EGFR staining was restricted to clusters of cells in in 30% of grade II chondrosarcoma tumor biopsies, suggesting that activation of EGFR is an event that occurs during chondrosarcoma tumor progression." (PMID 31139331, 2019). "We next investigated whether chondrosarcoma cell migration, that may influence metastatic phenotype, is affected following EGFR inhibition." (PMID 31139331, 2019). "This indicates that monoclonal antibodies therapy may be beneficial for the treatment of chondrosarcoma with activated EGFR through a paracrine/autocrine loop." (PMID 31139331, 2019). "We showed above that EGFR is activated in chondrosarcoma cells." (PMID 31139331, 2019). "To test this hypothesis, we assessed the effect of inhibition of EGFR on the proliferation of human chondrosarcoma cells." (PMID 31139331, 2019). "Taken together, our study reveals that EGFR is activated predominantly in high-grade chondrosarcoma tumors and may be used as a biomarker of chondrosarcoma cancer progression." (PMID 31139331, 2019). "Altogether, these results strongly support the notion that aberrant activation of EGFR is critical for chondrosarcoma tumor growth and survival and may contribute to progression to higher-grade lesion." (PMID 31139331, 2019). "Given that SW1353 chondrosarcoma cells express high amount of EGFR, we examined whether incubation of SW1353 cells with conditioned medium from HEMC-SS cells induces the phosphorylation of the receptor." (PMID 31139331, 2019). "Interestingly, inhibition of EGFR following treatment with AG1478 markedly decreased the activation of mTOR, therefore suggesting that EGFR mediates the activation AKT/mTOR signaling pathways in HEMC-SS chondrosarcoma cells." (PMID 31139331, 2019). "This study reveals that activation of EGFR is a key event that drives tumorigenesis in chondrosarcoma and suggests that inhibition of EGFR by a selective TKI or neutralizing antibodies may constitute a potential treatment for chondrosarcoma tumors." (PMID 31139331, 2019). "Treatment of chondrosarcoma cells with AG1478 strongly inhibits the phosphorylation of EGFR." (PMID 31139331, 2019).
chondrosarcoma (continued). "In addition, our results showed that inhibition of EGFR produced a cell cycle arrest at G0/G1 phase and induced apoptosis of chondrosarcoma cells." (PMID 31139331, 2019). "This study also reveals that constitutive EGFR activation drives the oncogenic signals in chondrosarcoma and suggests that inhibition of EGFR by TKIs or neutralizing antibodies may be proven effective in the treatment of high-grade chondrosarcoma." (PMID 31139331, 2019). "Most important, we found that EGFR is activated through an autocrine loop and showed that inhibition of EGFR profoundly reduced the activation of both ERK1/2 and AKT/mTOR signaling and decreased cell proliferation and migration of chondrosarcoma cells." (PMID 31139331, 2019). "We found that the TKI induced apoptosis in chondrosarcoma cells as evidenced by activation of Caspase-3 and cleavage of PARP, indicating that EGFR activation is required for chondrosarcoma survival." (PMID 31139331, 2019). "Analysis of the phosphorylation status of EGFR indicated that the receptor is activated in CH2879 cells, suggesting that EGFR receptor is aberrantly activated in these grade III chondrosarcoma cells." (PMID 31139331, 2019). "MiR-342-5p did not have any significant effect on EGFR protein expression in any of the three chondrosarcoma cell lines." (PMID 34070455, 2021). "To determine whether EGFR activation contributes to progression to a higher grade lesion, we used chondrosarcoma cells, CH2879 that were established from grade III chondrosarcoma tumor of bone." (PMID 31139331, 2019). "Given that EGFR activation triggers known oncogenic signals such as ERK1/2 and AKT and promote malignant phenotype, we analyzed the activation status of these pathways in HEMC-SS and SW1353 chondrosarcoma cells, and in human primary chondrocytes." (PMID 31139331, 2019). "Treatment of HEMC-SS chondrosarcoma cells cultured in 3D with AG1478 at 1 μM and 5 μM inhibits the phosphorylation of EGFR and reduced the activation of both ERK1/2 and AKT signaling pathways, however the inhibition is more pronounced when 5 μM of AG1478 were used." (PMID 31139331, 2019). "Therefore, it is important to evaluate the effect of the EGFR inhibitor, AG1478 on chondrosarcoma cells cultured in 3D system." (PMID 31139331, 2019). "Here, we showed that AG1478 treatment of HEMC-SS chondrosarcoma cells inhibits the expression of MMP-13 and MMP-3, suggesting that inhibition of EGFR may impair metastatic potential of chondrosarcoma." (PMID 31139331, 2019). "Indeed, all grade III and grade II chondrosarcoma tumor biopsies analyzed were stained positively for phosphorylated EGFR, however no staining was observed in grade I tumors." (PMID 31139331, 2019). "In contrast, treatment of SW1353 chondrosarcoma cells with the EGFR inhibitor, AG1478 did not induce significant cleavage of both Caspase 3 and PARP, suggesting that survival of these tumors may involve signaling pathways other than the EGFR pathway." (PMID 31139331, 2019). "We found that EGFR is activated in grade II and grade III chondrosarcoma tumors but not in grade I tumors, suggesting a role in tumor progression." (PMID 31139331, 2019). "We found that EGFR is activated in grade II and grade III chondrosarcoma tumors but not in grade I tumors." (PMID 31139331, 2019).
cystic fibrosis (11 papers, 2015 to 2026). Autosomal recessive disorder caused by pathogenic variants in the CFTR gene (cystic fibrosis transmembrane conductance regulator), which encodes a chloride and bicarbonate channel expressed in epithelial cells, and follow the diagnosis criteria. "CFTR regulates cystic fibrosis transmembrane transduction, which mainly regulates cell water content by activating the chloride pathway, whereas EGFR can also cause intestinal edema by inhibiting cell growth." (PMID 39597698, 2024). "The epidermal growth factor receptor influences how airway neutrophils clear bacteria in cystic fibrosis, revealing a novel mechanism in neutrophil biology." (PMID 41979898, 2026). "Consequently, a disturbance in the control of the complex EGFR/ADAM17/STAT3 pathway would likely play a role in Cystic Fibrosis and COPD chronic lung disease." (PMID 29540993, 2018).
E. coli infection (11 papers, 2016 to 2024). "Therefore, we hypothesize that the increase in EGFR might be caused by E. coli infection and subsequent TNF-α release, thereby amplifying AREG function." (PMID 30524196, 2018). "In contrast to Bcl-2, the increase in Bcl-XL in response to both AREG and E. coli infection was abolished by EGFR inhibition." (PMID 32082070, 2019). "It was already shown that TNF-α induces upregulation of EGFR, and in a previous study, we demonstrated that E. coli infection leads to TNF-α release, while PBMO displayed a distinctly increased TNF-α release compared to CBMO." (PMID 30524196, 2018). "Because actin cytoskeleton rearrangement is known to be one of the indispensable prerequisites for bacterial invasion, we therefore explored the possible relationship between EGFR activity and cytoskeleton alteration during meningitic E. coli infection." (PMID 30687645, 2018). "We show that cell surface EGFR is increased in response to E. coli infection, matching the results of another study that demonstrated upregulation of EGFR upon Helicobacter pylori infection." (PMID 30524196, 2018). "We therefore investigated the possible dimerization forms in response to meningitic E. coli infection, and an obvious heterodimerization of EGFR and ErbB3 was observed in the hBMECs upon infection." (PMID 30687645, 2018). "In both cell types, surface expression of EGFR was found significantly increased in response to E. coli infection." (PMID 30524196, 2018). "Collectively, these results provide evidence that meningitic E. coli infection induced the heterodimerization of EGFR–ErbB3 in hBMECs, which is important for EGFR activation and bacterial invasion." (PMID 30687645, 2018). "In our previous study using a porcine IPEC-J2 IEC model of E. coli infection, L. rhamnosus pretreatment suppressed EGFR activation and enhanced Akt activation." (PMID 29403451, 2017). "In our study, we found that the same microbial factors involved in EGFR activation also contributed to S1P generation in response to E. coli infection in HBMEC." (PMID 27711202, 2016). "Besides, U251 cells exhibited the significant downregulation of EGFR in response to meningitic E. coli infection." (PMID 33985523, 2021). "Therefore, we next investigated the possible dimerization of EGFR in hBMECs in response to meningitic E. coli infection." (PMID 30687645, 2018). "At this time point, it is hard to tell whether the delayed EGFR phosphorylation we observed results from insufficient knock-down of ErbB3, or whether some degree of EGFR homodimerization existed in the hBMECs in response to meningitic E. coli infection." (PMID 30687645, 2018). "Our previous study also suggests that L. rhamnosus ATCC7469 promotes EGFR and Akt activation in a time-dependent manner and that it can maintain IPEC-J2 cell barrier function, thus limiting extracellular E. coli infection." (PMID 29403451, 2017). "Our data demonstrate for the first time a novel role of S1P and a potential crosstalk between EGFR and SphK2-S1P-S1P2 signaling in HBMEC upon meningitic E. coli infection." (PMID 27711202, 2016). "After stripping, the membrane was re-probed for EGFR, showing an unchanged level of EGFR upon E. coli invasion, consistent with our earlier demonstration of no change in EGFR expression in response to meningitic E. coli infection." (PMID 27711202, 2016). "Therefore, we measured both cleaved caspase-9 and caspase-3 in response to E. coli infection and phagocytosis of E. coli and investigated whether AREG stimulation is capable of inhibiting the cleavage by preventing the formation of MAC via EGFR." (PMID 32082070, 2019).
Ewing sarcoma (11 papers, 2008 to 2025). A small round cell tumor that lacks morphologic, immunohistochemical, and electron microscopic evidence of neuroectodermal differentiation. "Biochemical and histological/immunohistochemical ex vivo analyses confirmed a reduced activation of ERBB4, EGFR, INSR, IGF1R, associated with apoptosis induction and angiogenesis inhibition in a drug-treated Ewing's sarcoma family tumor xenograft." (PMID 27374103, 2016). "Two Ewing sarcoma cell lines investigated showed high levels of nuclear EGFR expression as well as moderate expression in plasma membrane and cytoplasm." (PMID 18177496, 2008). "Alternatively, resistance to anti-IGF-1R treatment in Ewing's sarcoma could be related to the activation of alternate signaling pathways including EGFR and IR." (PMID 22022506, 2011). "As Ewing tumor cells do not seem to depend on EGFR and VEGFR pathways for survival, other key factors in the cellular signaling of Ewing sarcoma should be targeted in order to obtain a potent therapeutic response." (PMID 18177496, 2008). "We conclude that the sole inhibition of EGFR or VEGFR-2 signaling in Ewing sarcoma cell lines is not sufficient to inhibit tumor cell proliferation other than through unspecific toxicity." (PMID 18177496, 2008). "None of these complexes could mediate Alexa488-siRNA transport into EGFR-negative cells such as the Ewing sarcoma cell line SK-N-MC." (PMID 35220407, 2022). "The Ewing sarcoma SK-N-MC line is not an EGFR driven cancer since it lacks EGFR expression." (PMID 23166750, 2012). "Hence, the survival of Ewing sarcoma cells in culture does not seem to depend on EGFR or VEGFR signaling alone." (PMID 18177496, 2008).
Fanconi anemia (11 papers, 2017 to 2026). Fanconi anemia (FA) is a hereditary DNA repair disorder characterized by progressive pancytopenia with bone marrow failure, variable congenital malformations and predisposition to develop hematological or solid tumors. "Previous studies showed that ANKRD13B and FANCE were associated with epidermal growth factor receptor (EGFR) activation and Fanconi anemia, respectively." (PMID 34917510, 2021). "These cells harbor EGFR-activating mutations as drivers, which correlate with a Fanconi anemia (FA)-like cellular phenotype reported to be a synthetic lethal factor for ATR inhibition." (PMID 34316685, 2020). "EGFR TKI were granted orphan drug status by the European Medicines Agency for the treatment of HNSCC in the setting of Fanconi Anemia based on promising findings in cell line xenograft studies." (PMID 35158773, 2022). "Next, we determined whether the impaired Fanconi anemia pathway disrupted by ERCC1 affected the downstream homologous recombination (HR) repair pathway in EGFR exon 19 deletion NSCLC cells." (PMID 31875360, 2020). "The vast majority of HNSCCs arise in individuals without Fanconi Anemia, and the role of EGFR and NSAIDs remains unproven." (PMID 35158773, 2022).
glomerulosclerosis (11 papers, 2015 to 2025). A hardening of the kidney glomerulus caused by scarring of the blood vessels. "The deletion of selective podocyte EGFR led to marked reduction in albuminuria and glomerulosclerosis, and relative podocyte preservation in db/db mice, and regulating the activity of EGFR reduced the production of ROS." (PMID 37954274, 2023). "In CKD, the increase in Ang-II induces disintegrin and metalloproteinase-17 (ADAM17) expression, which activates the epidermal growth factor receptor/mitogen-activated protein kinase (EGFR-MAPK) pathway implicated in fibrosis, glomerulosclerosis, tubular dilation and atrophy." (PMID 36079742, 2022).